TNF (tumor necrosis factor)
Diseases named in the same sentence as TNF in open-access papers (continued):
Sharing a sentence is not in itself a finding about the gene and the disease.
infection (continued). "In addition it has been shown that ACs influence host parasite interactions through the modulation of tumor necrosis factor alpha (TNF-α) and that AC activity of lysed trypanosomes contributes to establishing an infection of these parasites in a host." (PMID 26441645, 2015). "Therefore, qRT-PCR analysis of IFNβ, OAS1, MxA, TNFα, IL-6 and viral RNA (vRNA) expression was performed in the context of WNVNY99 and WNVNSW2011 infections." (PMID 25884341, 2015). "In our in vitro granuloma model, at 24 h post-infection with M. tuberculosis H37Ra, we observed significant induction of a number of proinflammatory immune signaling pathways dependent on chemokines, IFN-γ and TNF." (PMID 26019382, 2015). "There was little change in any transcript upon infection in the absence of antibody, consistent with the NFκB and TNFα induction data." (PMID 26506431, 2015). "The temporal profile of TNF production by S. pyogenes-infected cells was consistent with a largely host cell surface-localized TLR2-dependent S. pyogenes recognition early in the infection and an endosome-dominated recognition in the later phase." (PMID 25756897, 2015). "This study examined the mechanism underlying this phenomenon by measuring the expression of antiviral genes—tumor necrosis factor alpha (TNF-α) and GTPase myxovirus resistance 1 (MX1)—in G6PD-knockdown cells upon human coronavirus 229E (HCoV-229E) and enterovirus 71 (EV71) infection." (PMID 26694452, 2015). "In contrast to D39, D39Δcps did not induce TNF-α and IL-6, and triggered low levels of KC in the lung 6 hours after intranasal infection." (PMID 25700108, 2015). "WNV also induces a dramatic increase in several pro-inflammatory cytokines such as tumor necrosis factor alpha (TNF-α) and interleukin (IL)-1β and chemokines such as CCl2 and CXCL10, which regulate leukocyte trafficking into the brain and neuronal death after infection." (PMID 26392176, 2015). "IFN-γ+TNF-α+IL-2+ multifunctional CD4+ T cells were present in the blood of all infected animals at one or two weeks after primary infection and their frequency increased in four out of six animals after homologous secondary infection." (PMID 25971313, 2015). "The proximal region of the TNFα promoter (~200 bp upstream of the TSS) regulates the transcription of TNFα in multiple cell types that respond to various stimuli including the T cell and B cell activation, infection and cytokines." (PMID 26406892, 2015). "SBCMV infection of this IBRB Tricell mixture for 96 hours resulted in increased levels of IL-6, MMP9, and stem cell factor with a concomitant decrease in granulocyte-macrophage colony-stimulating factor and TNF-alpha." (PMID 25573478, 2015). "No direct effect of α-toxin on TNF-α release was observed in thigh tissues, which represented the localised site of infection." (PMID 25675415, 2015). "It has been shown earlier using bone marrow reconstitution that changes in the lymphoid organs due to the absence of TNF signaling only have a minimal influence on the clinical outcome of the infection." (PMID 26834705, 2015). "The lack of effect of RIG-I on the induction of TNF-α by HCV was also confirmed by the infection of Huh7.5 cells with HCV." (PMID 26023919, 2015). "Our findings suggest that defects in CFTR may increase susceptibility of mice to lung infections with the highly mucoid serotype 3 Sp despite similar lung histopathology and levels of TNF- α and CXCL1/KC produced early in infection." (PMID 26469863, 2015). "However, at 8 hours post infection, depletion of STING partially reduced TNFα transcription induced by AdV+IgG, while depletion of MAVS reduced transcription upon infection with either AdV+IgG or HRV+IgG." (PMID 26506431, 2015).
infection (continued). "The signature also performed better than a wide range of host-proteins with an established role in the immune response to infection, including bacterial-related (e.g. TREM, IL-6 and IL-8), virus-related (e.g. IFN-γ and IL-2), and inflammation-related (e.g. IL-1a and TNF-α) proteins (P<10–8)." (PMID 25785720, 2015). "Thus, TLR4 can upregulate the expression of cytokines, such as TNF-α, IFN-γ, IL-6, IL-8, IL-12, and IL-10, thereby increasing resistance to pathogen invasion and infection." (PMID 26576220, 2015). "In comparison to previous expression studies from our population, genes encoding mediators of the inflammatory response exhibited an elevated expression of inflammatory cytokines such as TNFα, IL-1β, and MIP-1α in fundic and pyloric abomasa 7 days post infection." (PMID 25803687, 2015). "Failure to control M. tuberculosis replication results in bacilli dissemination and subsequent infection of peripheral organs including the central nervous system where infection of neurons can occur independent of TNF." (PMID 26112704, 2015). "Nevertheless, we have to keep in mind the anti-TNF-alpha experience where the initial results with the anti-TNF agent infliximab were also particularly promising, but subsequent increase in mortality and a high rate of infection led to trials termination." (PMID 26107937, 2015). "After infection with LmOVA, both WT and ACC2ΔT mice exhibited equivalent expansion of OVA-specific CD8+ T cells as well as efficient expression of effector molecules, such as IFN-γ, TNF-α, and granzyme B." (PMID 26367121, 2015). "Together, these results indicate that infection, IFNγ and TNFα have negative effects on mitochondrial respiration, which is alleviated by IL-4, while IL-6 afforded some protection, but only against loss of complex-IV." (PMID 26481427, 2015). "After infection, CD11b+Ly-6Chi monocytes emigrate from the bone marrow (BM) into the bloodstream through CCR2-receptor–mediated signaling and differentiate into dendritic cells (DCs) that produce tumor necrosis factor (TNF)-α and nitric oxide (NO)." (PMID 26618488, 2015). "It has been suggested that lower expression of TNFα, along with IFNγ, in SUDV infection may contribute to the longer time to death observed in SUDV infection as compared to EBOV." (PMID 26512687, 2015). "TNF-α and IFN-γ promote the development of an effective Th1 response that is necessary for the successful clearance of the virus, and chemokines secreted by NK cells also have an important role in the recruitment of other immune cells to the site of infection." (PMID 25915748, 2015). "The synthesis of appropriate amounts of tumor necrosis factor (TNF-α), IL-1 and IL-6 is clearly beneficial in response to infection, but higher levels may be relevant for immunopathological processes." (PMID 26362860, 2015). "Similar antibody potentiation of NFκB activation was observed during infection by the picornavirus human rhinovirus type 14 (HRV), although both NFκB and TNFα could be observed at a high viral dose." (PMID 26506431, 2015). "This protective immune response involves the releasing of cytokines such as tumor necrosis factor α (TNF-α), interleukin 8 (IL-8), IL-6, IL-12 and interferon γ (IFN-γ) which lead to classical activation of macrophages and their recruitment to the infection site." (PMID 25799044, 2015). "TNF is not typically detectable in healthy individuals, but serum and tissue levels are elevated under of inflammatory and infection." (PMID 25762127, 2015). "In fact, TNF-α acts synergistically with IFN-γ to stimulate the production of NO by macrophages and influences the expression of chemokines, such as CCL5, CCL9, CXCL10, and CCL2, which induce migration to and maintenance of immune cells in the infection site." (PMID 26495323, 2015).
infection (continued). "It should be stated that the experimental set-up in this study was performed to define the action of TNF during infection and not to investigate the effect as add-on therapy for asthmatic subjects exposed to infections." (PMID 26494305, 2015). "P. vivax infection reduces the numbers of different subsets of CD8+ T cells, particularly the memory cells, during blood-stage of infection and enhances the number of CD8+ memory T cells expressing IL-10, which positively correlates with the number of cells expressing TNF-α and IFN-γ." (PMID 25636730, 2015). "Also, the mRNA levels of iNOS and inflammatory cytokines, IL-1β, TNF-α, and IFN-γ, were upregulated after infection with E. papillata, whereas PPE significantly reduced the expression of these genes." (PMID 25654088, 2015). "To further confirm the role of NF-κB in the virus-induced upregulation of the TNF-α and MX1 genes, we treated A549 cells with BAY 11-7085, a specific NF-κB inhibitor, and examined the temporal change in the expression of antiviral genes after infection." (PMID 26694452, 2015). "Consistent with this, PFA-crosslinking of adenovirus before incubation with antibody prevented TNFα transcription at 8 hours but not 4 hours post-infection." (PMID 26506431, 2015). "We did not observe significant differences in IFN-γ or TNF-α mRNA levels at 2 weeks post-infection, when bacterial titers of perM::tn were 3-fold lower than those of wt." (PMID 25658098, 2015). "The finding that the induction of TNF-α was detected almost immediately after infection without the apparent need of an intact HCV genome suggested an early event of HCV infection in the induction of TNF-α, possibly during the viral entry." (PMID 26023919, 2015). "Also, this result was in contrast with a previous study in which TLR3−/− mice showed reduced cytokine (e.g., TNF-α and IL-6) responses, BBB permeability, neuroinvasion, and mortality following infection with mammalian cell-passaged WNV." (PMID 25188232, 2014). "Unlike IL-1β, IL-8, and TNFα, IL-6 transcription was significantly up-regulated 8 h after infection." (PMID 24712747, 2014). "Mouse macrophages that do not produce TNF have impaired Camp mRNA production upon infection or activation of TLR2, when compared to wild-type cells." (PMID 25400920, 2014). "In our hands, overproduction or inhibition of miR-155 in MDMs did not significantly alter TNFα mRNA levels (not shown) or TNFα secretion initiated by LVS or Schu S4 infection." (PMID 25295729, 2014). "Following the second TNFα activation at day 35, HA-CycT1-V107E stable cells were activated but quickly reverted back to basal HIV transcriptional levels and remained at these low levels at 60 days post infection." (PMID 24985467, 2014). "We observed that IFN-γ, TNF-α, IL-6 but not IL-10 production was increased initially 18 hours post-infection and decreased gradually thereafter following treatments with AMP and AZM." (PMID 24565171, 2014). "Prior infection did not reduce TNF-α response, arguing against a defect in the response to LPS and suggesting a specific defect in IL-12 and nitrite secretion." (PMID 25110400, 2014). "Infection with L. major increased the secretion of TNF-α, IL-6, TIMP-1, IL-1RA, G-CSF and TREM, but not IL-1α or IL-1β." (PMID 24416445, 2014). "Most of the significantly differentially expressed genes (SDEG) are part of immune cell networks such as tumor necrosis factor-alpha (TNF-α) and interferon-gamma (IFN-γ) regulon, indicating that infection by the mutant mounts a stronger host immune response compared to the wild type." (PMID 25201772, 2014). "Here, significantly higher levels of TNF-α were detected in primary infections but did not significantly differ between secondary and controls, though were generally lower." (PMID 25295285, 2014).
infection (continued). "Cytokine storm is characterized by abundant release of pro-inflammatory cytokines, such as IFN-γ, TNF-α and IL-6, as well as the anti-inflammatory cytokines such as IL-10; however, its mechanism of induction in oriential infection is not totally understood." (PMID 25254971, 2014). "So, herein we speculate that the blocking of CR3 during in vitro infection by dengue virus indirectly acts in CD16 surface of the monocytes, interfering on its TNF production." (PMID 25061945, 2014). "However, A/H7N9-infected C57BL/6 mice exhibited higher levels of IL-6, MCP-1, and IL-1β, but lower levels of TNF-α and IFN-γ, than A/H7N9-infected BALB/c mice at day 3 postviral infection." (PMID 24676272, 2014). "Our longitudinal analysis of individual patients with BUD showed that down-regulation of TNF-a is incomplete and fluctuant during treatment, suggesting that inflammation is tuned down by infection but not abolished." (PMID 24722524, 2014). "In summary, this study shows that feline epithelial endometrial cells produce TNFα as a result of LPS stimulation, which emphasizes the defensive role of epithelial cells during infections with Gram-negative bacteria." (PMID 25028529, 2014). "Viremia at 48 hours post infection was not different suggesting that the beneficial effect of anti-TNF-α therapy was not due to effects on viral replication." (PMID 24743949, 2014). "Here, cytokine and chemokine production during HSV-2 infection showed size-related differences for each nanoparticle type - presence of 13 nm AgNPs at the time of infection led to production of CCL2, IFN-γ and IL-10, while 33 nm AgNPs induced CCL2, TNF-α and IL-10." (PMID 25117537, 2014). "Compared to pathogenic mycobacteria, M. smegmatis is a potent inducer of TNF-α in macrophages, consistent with the elevated TNF-α levels in the supernatant of macrophages infection with MS_Vec instead of the non-infected groups." (PMID 24722253, 2014). "Besides activating complement, they limit infection by stimulating the secretion of interferon gamma (IFN-γ), IL-17, IL-6, tumor necrosis factor alpha (TNF-α), and nitric oxide (NO) by macrophages." (PMID 25654073, 2014). "Therefore, it is likely that increased TNF-α and IFN-γ released into the circulation after infection by the administration of S. pneumonia cells or their exotoxins demonstrated a detrimental effect on the host." (PMID 24565171, 2014). "Primary genital C. suis infection of the re-infection group (nine-week-old pigs) resulted in increased secretion of TNF-α, IL-1β, IL-6 and IL-12p40 by PBMC, whereas primo-infection of the infection group (seventeen-week-old animals) decreased the IL-1β, IL-8 and IL-10 secretion by PBMC." (PMID 25252649, 2014). "Therefore, the effects of W. chondrophila infection upon the expression of the pro-inflammatory cytokines, TNF-α, IL-1α, IL-1β and the chemokine CXCL8 was investigated 24 h post-infection." (PMID 25010668, 2014). "Neutrophils that are primarily recruited by CXCL8 can exert antiviral immunity amongst others by the release of inflammatory cytokines (e.g., IL-12, TNFα) and chemokines (e.g., CCL2, CXCL8, CXCL9, CXCL10) that leads to further recruitment of immune cells to the site of infection." (PMID 24646914, 2014). "Th1 type cytokines (IFN-γ, TNF-α) are involved in immune activation and then the injury of HBV antigen expressed hepatocytes, while Th2 type cytokine productions (IL-10, IL-4) inhibit immune reaction and involved in the persistence of infection." (PMID 25144199, 2014). "This is consistent with in vivo observations, where TNFα, IL-12 and IFNγ serum protein levels were not significantly elevated in B6 miR-146a−/− mice at 4 weeks post-infection, relative to B6 mice." (PMID 24967703, 2014). "After 12 months of follow-up, there were 15 unique cases (16%) of infections that did not require hospital admissions, and three adverse drug events were reported which resulted in discontinuation of anti-TNF agent therapy." (PMID 24883246, 2014).
infection (continued). "Our results demonstrate that the kinetics of TNFα induction in response to LVS or Schu S4, like induction of miR-155, was very low during the first 3 h after infection and then increased between 12 and 18 h, whereas the ELISA data confirm that F. tularensis-evoked cytokine secretion was very low." (PMID 25295729, 2014). "To test this, we infected cells with RGH and treated them with either DMSO or TNFα at four days post-infection rather than at the time of infection." (PMID 24502247, 2014). "The higher TNF and IFN-γ response observed in WT mice compared to Mif−/− mice during the chronic stage of infection could result from the reported positive feedback loop between MIF, TNF and IFN-γ." (PMID 25255103, 2014). "It is likely that the in vivo effect of down-regulation of CR expression on monocytes was attributable to cytokines, such as TNF-α, and other inflammatory mediators released during infection rather than directly to DENV." (PMID 25061945, 2014). "A recent publication reported that MC respond to intracellular, but not extracellular, poly(I:C) by inducing mainly IFNα and TNF-α; moreover, infection of MC with live Sendai virus induces an anti-viral response similar to that of intracellular poly(I:C)." (PMID 25359293, 2014). "The high levels of serum IFN-γ, but not those for TNF-α during an infection with S. mansoni is dependent on ligands for TLR2 and/or TLR4, because in mice deficient for both TLRs serum IFN-γ was low throughout the infection." (PMID 25398130, 2014). "TNF-α, IFN-γ, IL-6 are cytokines important for mounting a proper adaptive antiviral response to HSV-2, while CCL2 can attract monocytes and T cells to the site of infection." (PMID 25117537, 2014). "Tumor necrosis factor alpha (TNF-α) inhibitors including infliximab have shown significant effects in classic IBD, while there is a concern that these treatments can be accompanied by an increased vulnerability to infections in CVID patients." (PMID 24952714, 2014). "Conversely, post-infection treatment of the cells with LieIF/IFN-γ did not induce any up-regulation in MIP-1α or TNF-α mRNA expression." (PMID 24830439, 2014). "However, our data show that mRNA expression levels of both TNF-α and IFN-γ were comparable to the control mice, which died one to three days after infection." (PMID 24757289, 2014). "Furthermore, the data indicated decreased TNFα expression in the FK506-treated group at both the gene and the protein levels at 1 day post-infection (P<0.01, and P<0.01, respectively)." (PMID 25464008, 2014). "Upon infection with ECTV or VACV, p65 was retained in the cytoplasm following treatment with TNFα or IL-1β, indicating that ECTV could inhibit NF-κB despite the lack of orthologs of M2, K7, B14, A49, and A52." (PMID 25122471, 2014). "The authors hypothesize that MAPK p38 and ERK 1 pathways with respect to TNF-α production, as well as the MAPK p38 and ERK 1 and 2 pathways in relation to IL-10 production under infection by C. pseudotuberculosis are important regulators of cellular response." (PMID 25179342, 2014). "In this manuscript we show that TNFα adds significantly to the proinflammatory effects of viral RNA on endothelial cells and therefore plays an important role in the initiation and propagation of vascular manifestations of HCV-infection." (PMID 25419735, 2014). "To identify host genes and gene polymorphisms critical for the differences during the early stages of H5N1 disease we have performed a QTL analysis on genetically diverse strains of mice looking at the production of pro-inflammatory cytokines CCL2, TNF-α, and IFN-α, 48 hours post infection." (PMID 25418976, 2014). "The infection or the IFN-γ treatment did not change the basal level of TNF-α measured in untreated/uninfected control cultures." (PMID 25386119, 2014). "Although isolate 72 presented a higher TNF-α in the first 24 hours, flow cytometry revealed that this isolate in this period of infection did not induce an increase in cell apoptosis." (PMID 25299837, 2014).